CD4 (CD4 molecule)
Diseases named in the same sentence as CD4 in open-access papers (continued):
Sharing a sentence is not in itself a finding about the gene and the disease.
acute lymphoblastic leukemia (37 papers, 2007 to 2026). Leukemia with an acute onset, characterized by the presence of lymphoblasts in the bone marrow and the peripheral blood. "The role of CD4+CD25+FOXP3+ regulatory T cells (Tregs) in acute lymphoblastic leukemia development has been linked to a higher immunosuppressive activity compared to the Tregs of healthy subjects, leading to the inhibition of anti-tumor immunity." (PMID 37569699, 2023). "Another study revealed the long-lived anti-CD19 CAR T cells in pediatric acute lymphoblastic leukemia (ALL) patients developed a CD4/CD8 DN phenotype with an exhausted-like memory state." (PMID 38659046, 2024). "Control cells included normal PBMC, isolated CD4+ T-cells and the T-cell acute lymphoblastic leukemia (T-ALL)-derived cell line Jurkat." (PMID 36072598, 2022). "CD4+CD25highCD127low/−FoxP3+ regulatory T cells (Tregs) are currently under extensive investigation in childhood acute lymphoblastic leukemia (ALL) and in other human cancers." (PMID 30003111, 2018). "In our study, for the first time, the percentage of individual subpopulations of regulatory T cells (Tregs) among CD3+CD4+ lymphocytes in the bone marrow and peripheral blood of children suffering from acute lymphoblastic leukemia were determined." (PMID 30003111, 2018). "Studies of CD19 CAR T cells in patients with lymphoma or acute lymphocytic leukemia (ALL) have demonstrated that peak levels of CAR T cells with a high CD8:CD4 T cell ratio, and higher numbers of CD8+ effector T cells, are associated with a better response." (PMID 28653584, 2017). "Over the past two decades a number of papers reported that over-activation of Notch signaling causes T cell acute lymphoblastic leukemia (T-ALL), a cancer that prominently features circulating monoclonal CD4/CD8 double positive T cells in different mouse models." (PMID 24386421, 2013). "In addition, SUP-T1 cells (lymphoblastic lymphoma-derived CD4+ T cell line), and the acute lymphoblastic leukemia-derived CD4+ T cell lines CEM and MOLT-3, were evaluated by immunoblot with these antibodies." (PMID 38675845, 2024). "Furthermore, the cytotoxicity of compound 1 (PT162, NSC 796018) towards CCRF−CEM cells (ATCC® CCL-119TM, acute lymphoblastic leukemia cells, tumorigenic CD4+ T lymphoblasts) and Vero cells [African green monkey (grivet) Chlorocebus aethiops (syn." (PMID 38398665, 2024). "Also, RUNX1 binds to NFATC2 promotor region in CD4 T cell of mouse and human, and Jurkat T cell acute lymphoblastic leukemia cell line." (PMID 35844683, 2021). "In our study, we investigated a population of CD4+CD25highCD127low/–FoxP3+ regulatory T cells in the bone marrow and peripheral blood of children with acute lymphoblastic leukemia treated in the Department of Pediatrics, Hematology and Oncology, Medical University of Gdansk in 2011–2016." (PMID 30003111, 2018). "Glutamine deprivation in the lymphoblastic leukemia CD4+ (CEM clone 13) cells, human lymphoblastic leukeumia (CEM-CCRF) cells and human promyeloblast (HL-60) cells also led to cell shrinkage and activation of CD95 receptors suggesting extrinsic pathway involvement." (PMID 26225207, 2015). "Finally, to assess B7-H3 and LAG3 expression on CD4 CTLs in human tumor tissues, we analyzed bone marrow aspirates from twelve pediatric patients diagnosed with B-cell acute lymphoblastic leukemia (B-ALL)." (PMID 40070836, 2025). "Furthermore, B7-H3+LAG3+ CD4+ T cells were induced during co-culture with bone marrow cells from pediatric patients with B-cell acute lymphoblastic leukemia (B-ALL)." (PMID 40070836, 2025). "As in the case of patients with acute lymphoblastic leukemia, adults with AML also had a higher percentage of CD4+CD25high T-cells in PB." (PMID 30944830, 2019). "Patient 2 presented with a CD4+ pediatric T-cell acute lymphoblastic leukemia (T-ALL)." (PMID 29348865, 2017). "CD4+ acute lymphoblastic leukemia (ALL) T cell lines, primary PBMC, and CD4+ T cells from healthy donors served as HTLV-negative controls." (PMID 19014482, 2008).
acute lymphoblastic leukemia (continued). "This study aims to determine whether HVEM is an immune checkpoint target with inhibitory effects on anti-tumor CD4+ T cell responses in vitro and whether HVEM gene expression is dysregulated in patients with acute lymphocytic leukemia (ALL)." (PMID 38785930, 2024). "For each co-culture, CD4CAR or vector control NK-92 effector cells were incubated with tumor cells that were comprised of equal numbers of on-target CD4+ cells, CFSE-stained KARPAS-299 or CFSE-stained CCRF-CEM, and “off-target” CMTMR-stained CD4-, CD5+ MOLT4 acute lymphoblastic leukemia cells." (PMID 29348865, 2017). "Recently, it was shown that this can be accomplished in CD4+ T cells with the use of dasatinib, a Bcr-Abl-specific TKI that has been approved for use in chronic myelogenous leukemia (CML) and Philadelphia chromosome-positive acute lymphoblastic leukemia (Ph+ AML) by the FDA." (PMID 29764952, 2018). "Overexpression of TIM-3 on exhausted CD4+ and CD8+ T cells and leukemic cells in patients with chronic lymphocytic leukemia (CML), acute lymphoblastic leukemia (ALL), and CLL, might be a prognostic factor for poor therapeutic response and relapse in patients." (PMID 40647414, 2025). "Of the 6 RGS-treated animals that eventually succumbed to a lethal myeloproliferative disorder, 5 simultaneously developed T-cell acute lymphoblastic leukemia (T-ALL)/ thymic lymphoma with a predominance of CD4+CD8+ and CD8+ cells (data not shown)." (PMID 30956775, 2019).
colorectal tumors (37 papers, 2006 to 2025). "Increased CD4 + lymphocyte infiltration has also been found to be associated with improved survival in mismatch repair proficient colorectal tumours." (PMID 37171483, 2023). "For instance, a recent study found that a majority of CD4 T cells found in lung and colorectal tumors are likely tumor‐unspecific bystander cells." (PMID 40923840, 2025). "In this study, we found that in colorectal tumor models, simultaneous PD-L1 blockade and CD4+ T cell depletion induced tumor vascular normalization, which was positively correlated with tumor regression." (PMID 36969495, 2023). "A critical role of human CD4 cytotoxic T lymphocytes in mediating tumor clearance independent of CD8 T cells is reported in humanized immune system mice implanted with HT-29 colorectal tumors." (PMID 37185301, 2023). "In the CT26 colorectal tumor model, anti-PD-L1 therapy or CD4+ T cell depletion alone retarded tumor growth, while CD8+ T cell depletion did not influence tumor growth." (PMID 36969495, 2023). "Single-cell RNA (scRNAseq) profiling of colorectal tumor specimens has revealed a Th1-like CD4 cluster that expresses both Th1 and cytotoxic markers." (PMID 37185301, 2023). "Here, we found that anti-PD-L1 therapy coupled with CD4+ T cell depletion induced colorectal tumor regression and vascular normalization, while monotherapy only retarded tumor growth without affecting the tumor vasculature." (PMID 36969495, 2023). "Western blotting analysis of the colorectal tumors confirmed that treatment with 0.3 g/kg of ZQFZ significantly upregulated the expression levels of CD4 by 65.16% (p < 0.01) and of CD8 by 50.63% (p < 0.001), compared with their levels in control mice." (PMID 35680568, 2022). "In this study, we phenotypically characterized CD3+CD4- (CD8+) T cells in colorectal tumor tissues (TT), normal colon tissues (NT) and in circulation of CRC patients." (PMID 35804964, 2022). "Consistently, numbers of CD4+ PU.1+ T cells were significantly increased in colorectal tumours, thereby suggesting the presence of Th9 cells." (PMID 35793807, 2022). "We found that CD4+ T cells were significantly higher in colorectal tumors, compared with normal colon tissues." (PMID 31921188, 2019). "We found that CD4+CD25+FoxP3+ Tregs accumulate in colorectal tumors at significantly higher levels, compared to periphery and adjacent colon normal tissues." (PMID 31921188, 2019). "Together, these data demonstrate for the first time thata new ST2L+CD4+CD25+ T-cell subset with suppressivefunctions is present in colorectal tumors of mouse model." (PMID 29950152, 2018). "In the ACT setting where exogenous tumor-reactive T cells were infused to CTX-conditioned mice, antibiotics administration reduced the efficacy of tumor-specific CD4+ T cells in a colorectal tumor model." (PMID 29340102, 2017). "In a colorectal tumor model, tumor-specific CD4+ T cells derived from TCR transgenic (TCR-Tg) mice were used, modeling the clinical use of selected tumor-reactive T cell clones or T cells engineered to express tumor-specific TCRs." (PMID 29340102, 2017). "In the ACT setting, antibiotics administration impaired the therapeutic effects of adoptively transferred tumor-specific CD4+ T cells in mice with implanted colorectal tumors." (PMID 29340102, 2017). "An increased frequency of CD4 T cells producing IL-17 (Th17 cells) was observed in colorectal tumor tissue compared with adjacent uninvolved tissue." (PMID 27014625, 2016). "Single cell suspensions obtained from both colorectal tumors and adjacent uninvolved tissue were stained for markers of Treg cells, including CD4, CD25, CD127, FOXP3, and CD39, and were analyzed by flow cytometry." (PMID 27014625, 2016).
colorectal tumors (continued). "There was a significant increase in the frequency of total CD3+ (p < 0.01) and CD4+ (p < 0.05) T cells producing IL-17, indicating that the local microenvironment of colorectal tumors can selectively enhance Th17 cell polarization or recruitment." (PMID 27014625, 2016). "Representative dot plots show staining controls in peripheral blood and PD-1 expression by colorectal tumor infiltrating CD4+ T cells or CD8+ T cells." (PMID 27014625, 2016). "An earlier study stated that the expression of CCR5 and CXCR3 has a positive correlation with the accumulation of CD8+ and CD4+ T lymphocytes in invasive colorectal tumors." (PMID 24565056, 2014). "Decreased total numbers of the CMI promoting Th1 CD4+ cells have been found in patients with colorectal tumours." (PMID 16641913, 2006). "This PTX-loaded nano drug delivery system demonstrates enhanced treatment efficacy in colorectal tumor-bearing mice and, furthermore, modulates the tumor immune microenvironment, including increased activation of CD4+ and CD8+ T cells, M1 macrophage polarization, and Treg cell downregulation." (PMID 38612457, 2024). "Moreover, tumor regression by the combination of PD-L1 blockade and CD4+ T cell depletion is positively correlated with tumor vascular normalization in colorectal tumor models." (PMID 36969495, 2023). "Thus, this study emphasizes CD8+ T cells as a major immune effector while CD4+ T cells as a major immune suppressor in anti-PD-L1 therapy in colorectal tumors." (PMID 36969495, 2023). "Thus far, our data have shown that CD4+ T cells hinder the effects of anti-PD-L1 therapy on either tumor growth or the tumor immune microenvironment in the CT26 colorectal tumor model." (PMID 36969495, 2023). "However, if the colorectal tumors have both HLA-A/B/C expression high and T (CD4+ T and CD8+ T) cell infiltration high, the patients have a significantly better prognosis (p = 0.0002)." (PMID 36551849, 2022). "Moreover, IL-17 secreting CD4+ T cells infiltrated in colorectal tumors can coproduce TNF-α and IL-10." (PMID 33327620, 2020). "Therefore, we focused our subsequent investigations to perform further phenotypical characterization of CD4+ T cell subsets to ascertain their role in colorectal tumor biology." (PMID 31921188, 2019). "Finally, the presence of a potent suppressive CD4+Foxp3− T cell population was revealed within the colorectal tumor regulatory landscape by comparison of healthy colon, colorectal tumor samples, and matched blood from CRC patients." (PMID 26605342, 2015). "Moreover the LAP+CD4+ sub-population cells were also found in colorectal tumors where their proportions within the CD4+ tumor-infiltrating T cell pool increased with disease progression." (PMID 23874342, 2013). "In both CT26 and MCA38 murine colorectal tumor models, we found that only the combination of PD-L1 blockade and CD4+ T cell depletion could induce tumor vascular normalization and tumor regression, indicating the contribution of vascular normalization to elicit durable antitumor immunity." (PMID 36969495, 2023). "We established the presence of CD45+CD4+CD25+CCR8+ ti-Tregs in MC38 and CT26 colorectal tumor models that constituted more than 40% of all tumors infiltrating Tregs." (PMID 41035646, 2025). "Together, these results suggest that anti-PD-L1 therapy induces tumor vascular normalization and colorectal tumor regression via CD8+ T cells, which is antagonized by CD4+ T cells." (PMID 36969495, 2023). "Here, we report potent CD4 T cell-mediated tumor regression and memory responses in humanized immune system (HIS) mice implanted with HT-29 colorectal tumors." (PMID 37185301, 2023). "First, we created a 7-plex immunofluorescent staining panel to be used on a colorectal tumor tissue (CRC1) consisting of a tumor marker (EPCAM), T-cell markers (CD3, CD4, and CD8), and myeloid markers (CD163, HLA-DR, and XCR1)." (PMID 37731497, 2023).
colorectal tumors (continued). "Simultaneous PD-L1 blockade and CD4+ T cell depletion activated CD8+ T cells and induced colorectal tumor regression, which was positively correlated with the induction of tumor vascular normalization." (PMID 36969495, 2023). "For example, CD8+ Tregs isolated from prostate or colorectal tumours are commonly characterized by CTLA-4 expression and TGF-β production, suppressing CD4+ T cell proliferation, Th1 cell expansion and their IFN-γ production ex vivo." (PMID 36319895, 2023). "ZQFZ upregulated the levels of CD4 and CD8 in the spleen and colorectal tumors and decreased the expression levels of cytotoxic T-lymphocyte-associated protein 4 and programmed death-ligand 1 in colorectal tumors." (PMID 35680568, 2022). "Concurrently, the protein levels of CD4 and CD8 in colorectal tumors of ApcMin/+ mice also increased significantly after ZQFZ treatment." (PMID 35680568, 2022). "In this study, we investigated CD3+CD4− T cells, which predominantly comprise CD8+ T cells, in colorectal tumor tissues (TT), and compared them with normal colon tissues (NT) and peripheral blood." (PMID 35804964, 2022). "After treatment with ZQFZ, the proportion of CD4- and CD8-positive cells in the spleen and colorectal tumors of ApcMin/+ mice increased significantly and the proportions of IFN-γ- and IL-4-expressing cells were also altered." (PMID 35680568, 2022). "Compared with the normal mesentery, the mesentery adjacent to the colorectal tumor showed increased B and regulatory T cells and decreased NK, CD3+ CD56+, CD4+ TRM, and CD8+ TRM cells." (PMID 34604029, 2021). "Pearson correlation of CD4+CD25+CD127+ T cells and infiltrating cytokine producing cells in colorectal tumors (n = 14)." (PMID 27014625, 2016). "There was a significantly increased expression of PD-1 on both CD4+ (p < 0.01) and CD8+ (p < 0.05) T cells within colorectal tumor tissue relative to adjacent uninvolved tissue." (PMID 27014625, 2016). "We observed increased expression of PD-1 on both CD4 and CD8 T cells infiltrating colorectal tumors." (PMID 27014625, 2016). "The frequencies of CD4 and CD8 T cells that produced cytokines or expressed the inhibitory molecule programed cell death 1 (PD-1) were determined by flow cytometry in colorectal tumor and matched uninvolved colonic tissue." (PMID 27014625, 2016). "Based on this finding, we further examined GSDMD activation in tumor-infiltrating CD4+ T cells of colorectal tumor tissues derived from patients responsive and patients nonresponsive to anti–PD-1 immunotherapy." (PMID 40759573, 2025). "Thus, our findings reveal the opposite roles of CD4+ and CD8+ T cells in anti-PD-L1 therapy and suggest a potential new strategy to potentiate anti-PD-L1 therapy by remodeling tumor blood vessels in colorectal tumors." (PMID 36969495, 2023). "In conclusion, anti-PD-L1 therapy induces tumor vascular normalization, decreases the proportions of intratumoral PD-L1+ lymphoid and myeloid cells, and inhibits colorectal tumor growth in a CD8+ T cell dependent manner, while CD4+ T cells antagonize those effects." (PMID 36969495, 2023). "CD4+CD25+CD127lo and CD4+CD25+CD127loFoxP3+CD39+ Treg cells were enriched in colorectal tumors." (PMID 27014625, 2016). "However, both the uninvolved normal tissue and colorectal tumor tissue were infiltrated by CD4+ and CD8+ T cells, with a CD4:CD8 ratio of approximately 2:1." (PMID 27014625, 2016). "Therefore, we investigated the expression of PD-1 on both CD4+ and CD8+ T cells in adjacent normal tissue and colorectal tumors by flow cytometry." (PMID 27014625, 2016). "In contrast, both CD4+ and CD8+ T cells, as well as CD4+ Foxp3+ regulatory T cells (Tregs) decrease significantly in the spleen, which leads to a reduction of all representative cytokines such as IFN-γ, IL-4, and IL-10 in allograft colorectal tumor models compared to normal controls." (PMID 30262787, 2018).
colorectal tumors (continued). "We found that mainly CD4+ T cells, rather than CD19+ B cells and CD8+ T cells, produce IL-9 in colorectal tumours." (PMID 35793807, 2022). "The mean densities of tumor-infiltrating CD4, CD8, CD56 immune cells were 620.2, 261.2, and 0.2 cells/mm2, respectively, in HIV-infected colorectal tumors compared with 698.6, 243, and 14 cells/mm2 in non-HIV-infected tumors." (PMID 35311077, 2022). "Although PD-L1 blockade or CD4+ T cell depletion alone had no impact on tumor vessel perfusion compared with control group, concurrent PD-L1 blockade and CD4+ T cell depletion significantly improved tumor blood vessel perfusion compared with all the other groups in the MCA38 colorectal tumor model." (PMID 36969495, 2023).